IL6 (interleukin 6)
Diseases named in the same sentence as IL6 in open-access papers (continued):
Sharing a sentence is not in itself a finding about the gene and the disease.
atherosclerosis (continued). "IL-6 is an inflammatory cytokine that plays a central role in propagating the downstream inflammatory response that sustains atherosclerosis progression, whereas IL-10 is a prototypic anti-inflammatory cytokine released by activated macrophages that delays the growth of vascular lesions." (PMID 32717800, 2020). "The genes regulating circulating levels of soluble gp130 (sgp130), the antagonist of the inflammatory response in atherosclerosis driven by interleukin 6, are largely unknown." (PMID 31932740, 2020). "Links between NETs and cytokine release have already been documented, e.g. NETs may induce the transcription of IL-6 and pro-IL-1β genes in macrophages in early atherosclerosis." (PMID 32685129, 2020). "Thus, the vicious cycle formed between OxLDL and the inflammatory cytokines (TNF-α and IL-6) from macrophages in the subendothelial space results in a persistent inflammatory response that promotes atherosclerosis." (PMID 32752134, 2020). "Specifically TNF-α and IL-6 are mentioned as being responsible for the reduction of NO production and, as a consequence, of endothelial dysfunction, which is considered a precursor to atherosclerosis and cardiovascular disease." (PMID 32486269, 2020). "In addition, IL-6 is a typical inflammatory factor in the process of atherosclerosis, and inhibiting the release of IL-6 and reducing its downstream expression can also have a huge antiatherosclerosis influence." (PMID 32733941, 2020). "Furthermore, as an important proinflammatory cytokine, IL-6 exerts a profound influence on STAT3-mediated inflammation in atherosclerosis." (PMID 31588227, 2019). "IL-1β represents the tip of the iceberg; there are several other potential inflammatory mediators that could be directly targeted to halt atherosclerosis progression, such as by directly targeting the inflammasome, IL-1α, IL-6, IL-18, and IL-33, among others." (PMID 31672136, 2019). "Furthermore, IL-6 contributes to the development of atherosclerosis through metabolic, endothelial and procoagulant mechanisms." (PMID 31906008, 2019). "Therefore, our study aimed to analyze the relationship between IL-6 level and other inflammations, atherosclerosis, and cardiac function parameters in early onset CAD patients." (PMID 31739518, 2019). "Furthermore, positive correlations between IL-6 and markers of atherosclerosis were mainly observed in patients older than ours." (PMID 31739518, 2019). "Therefore, the present study aimed to analyze the relationship between IL-6 level and other inflammations, atherosclerosis, and cardiac function parameters in early onset CAD patients." (PMID 31739518, 2019). "Similarly, blocking IL-6 by a specific antibody has shown a protective effect in atherosclerosis even though the results of this treatment are still unclear." (PMID 31191522, 2019). "However, IL-6 affected atherosclerosis through synergistic action with other inflammatory factors, subsequently leading to CVD." (PMID 31191115, 2019). "We thus determined whether exogenous anti-oxidant N-acetylcysteine administration reduces plasmas ROS and IL-6 levels induced by NaVO3 and rescues mice from NaVO3-induced atherosclerosis." (PMID 31817202, 2019). "The decreased plasma IL-6 level could, therefore, be partly responsible for the attenuation of atherosclerosis in SP-D/ApoE DKO mice, despite the elevated body weight and plasma lipoproteins, which are known risk factors for the development of CVD." (PMID 31616435, 2019). "We evaluated correlations between IL-6 and radiological parameters of atherosclerosis." (PMID 31739518, 2019). "This hypothesis is supported by anti-oxidant N-acetylcysteine (NAC) rescue of ApoE−/− mice from NaVO3-induced excessive plasma ROS and IL-6 and consequent atherosclerosis." (PMID 31817202, 2019).
atherosclerosis (continued). "Activation of FXR pathways in mouse models of atherosclerosis could almost completely inhibit aortic atherosclerotic lesion formation, attenuated the pro-inflammatory expression of IL1ß, IL6 and TNF and negatively modulated NFκB-mediated inflammation." (PMID 31191690, 2019). "Moreover, it is shown that activation of TLR4 and NF-κB increased the expression of IL-6 and adhesion molecules and decreased the activation of eNOS in atherosclerosis." (PMID 31336567, 2019). "Ceramides promote the secretion of IL-6 and C-reactive protein, increases ROS formation, promotes transcytosis of oxLDL across endothelial cells, and increases monocyte adhesion, thereby promoting inflammation and atherosclerosis." (PMID 31616435, 2019). "Given the increases of IL-6 from VSMCs and other vascular tissues, IH may facilitate macrophage foam cell formations in lesions, and thereby contribute to the progression of atherosclerosis." (PMID 31159449, 2019). "In addition, atomic bomb survivors exposed to high doses are more prone to the development of atherosclerosis and demonstrated signs of general inflammation, with increased levels of IL-6 and C-reactive protein (CRP)." (PMID 30377700, 2019). "IL-6 also plays an essential role in initiating and developing the process of atherosclerosis." (PMID 32802107, 2019). "In this study, we used an animal model of ApoE−/− mice to demonstrate that vanadium exposure has detrimental effects on increasing plasma ROS and atherosclerotic cytokine IL-6 and consequently promotes the synthetic phenotype in VSMCs, which leads to atherosclerosis." (PMID 31817202, 2019). "Also in the cardiovascular system disease, IL6 is an upstream inflammatory cytokine that plays a central role in propagating the downstream inflammatory response responsible for atherosclerosis." (PMID 31780867, 2019). "Beyond IL-1 and IL-6, several other chemokines are involved in atherosclerosis." (PMID 30873416, 2019). "In this group of patients, who had median FRS of 1% and all with an FRS <8%, traditional risk factors did not account for the high prevalence of sub-clinical atherosclerosis, but the authors found high IL-6 levels (>6.6 pg/mL) resulted in an odds ratio of 9 for sub-clinical atherosclerosis." (PMID 31275317, 2019). "Furthermore, in atherosclerosis, IL-6 produced by foam cells induces the production of small quantities of CRP." (PMID 31354915, 2019). "Clinical trials involving canakinumab, a monoclonal antibody against IL-1β, has shown a significant reduction of major cardiovascular incidents in patients with atherosclerosis, by reducing the total levels of plasma IL-6 and CRP compared to those given a placebo." (PMID 30333009, 2018). "Due to the well-established role of IL-6 in promoting atherosclerosis in humans, its increased biosynthesis seen in a rabbit model (particularly marked in a group exposed to oxysterols) appears to be a significant biomarker suggestive of chronic vascular wall inflammation." (PMID 29713239, 2018). "IL-6 is a multifunctional cytokine involved in several contradictory processes as ithas pro and anti-inflammatory effects and may promote atherosclerosis and muscleloss." (PMID 29944163, 2018). "However, in CAE, the levels of IL-6 were found to be higher than atherosclerosis, suggesting a pro-inflammatory response secreted by macrophages and T-cells." (PMID 29337902, 2018). "Therefore, decreasing IL-6 and IL-8 should be an important step in preventing the development of atherosclerosis." (PMID 29875665, 2018). "Among them, inflammation is a well-known cause of cardiovascular events; indeed, atherosclerosis is an inflammatory process; numerous inflammatory molecules including hs-CRP, IL-6, IL-1β and TNF-α are elevated in patients with myocardial infarction or unstable angina." (PMID 29439738, 2018). "Data on post-exercise changes of IL-6 levels in atherosclerosis related diseases are equivocal." (PMID 28291817, 2017).
atherosclerosis (continued). "Interleukin-6 (IL-6) plays a central role in atherosclerosis and inflammation." (PMID 28878828, 2017). "Increased plasma levels of IL-6 were associated with cardiovascular mortality over 5-year independent of other risk factor of atherosclerosis." (PMID 29312959, 2017). "A significant role of IL-6 in the pathophysiology of atherosclerosis has also been suggested." (PMID 28531207, 2017). "However, the pathophysiological pro-inflammatory actions of IL-6 in a variety of diseases, including atherosclerosis, are thought to be driven by aberrant IL-6 receptor “trans-signalling”." (PMID 29367551, 2017). "IL-6 stimulates growth of promoters of macrophage and vascular smooth muscle cells, which are major components of plaque, and IL-6 expression is also detected in human atherosclerotic lesions.These findings indicate that IL-6 participates in the development of atherosclerosis." (PMID 29312959, 2017). "Similarly, SLE patients with atherosclerosis showed increased levels of IL-6 and IL-17 compared with SLE alone and the controls." (PMID 29430084, 2017). "CREB also increases LPS and TLR4 dependent IL-6 production in vascular smooth muscle cells which may contribute to the vascular inflammation seen in atherosclerosis." (PMID 28545453, 2017). "Furthermore, the role of TNF-α, IFN-γ, IL-1β, IL-6, IL-8, IL-4 and IL-10 in the pathogenesis of atherosclerosis in carotid artery post-carotid endarterectomy has been documented." (PMID 27271180, 2016). "Moreover, evidence also highly suggested that IL-6 contributes to the pathogenesis of artery atherosclerosis via promoting local inflammatory lesions." (PMID 27034587, 2016). "Elevated levels of total cholesterol, PLTP, RANTES, IL-6, insulin and leptin, which showed correlation with 18F-FMCH uptake, have been linked with increased atherosclerosis thus lending support to the association between 18F-FMCH uptake and the risk of atherosclerosis." (PMID 26852231, 2016). "To study the local role of adipo/cytokines in atherosclerosis, we evaluated the presence of adiponectin, visfatin, lipocalin-2, resistin, IL-6 and TNFR2 in secretomes of the unstable carotid atherosclerotic plaque and non-atherosclerotic mammary artery tissue cultures." (PMID 27391230, 2016). "The over-expression of IL-6 is seen in many atherosclerosis studies." (PMID 27799085, 2016). "Furthermore, animal studies have shown that palm-derived TTMF treatment at dose (15 mg/kg) reduced the expression of IL-6 in the aorta of rabbits with established atherosclerosis." (PMID 27799085, 2016). "To determine whether exacerbated atherosclerosis with Ad-C5a treatment was correlated with increased inflammatory cytokines expression, we analyzed the plasma level of IL-6, IFN-γ and TNF-α in mice." (PMID 27517153, 2016). "Supplementation of lutein decreased serum IL-6 levels in atherosclerosis patients." (PMID 27047687, 2016). "Clinical studies convincingly demonstrated the elevation of IL-6 in patients with atherosclerosis." (PMID 27034587, 2016). "IL-6 is an inflammatory cytokine that is highly expressed during atherosclerosis." (PMID 27845432, 2016). "Similarly, increased plasma IL-6 is related to endothelial dysfunction and atherosclerosis development." (PMID 27166190, 2016). "IL-6 has been well studied particularly in the context of atherosclerosis." (PMID 26544186, 2015). "Clinical observations suggest that sleep disorders with decreases in deep sleep might serve to elevate nocturnal catecholamine levels and biomarkers of atherosclerosis such as interleukin-6." (PMID 25875738, 2015). "Moreover, authors found a reduction in sIL-6R in animals that received fish oil, which reinforces the role played by IL-6 trans-signaling in early stages of atherosclerosis development." (PMID 26578976, 2015). "IL-6 has several roles in the pathophysiology of atherosclerosis." (PMID 26075620, 2015).
atherosclerosis (continued). "It should also be noted that cancer cells are well known to secrete pro-inflammatory cytokines such as TNF-α, IL-6, and IL-1β; all of which act to promote a local, pro-neoplastic environment (which may also influence atherosclerosis)." (PMID 26000958, 2015). "Moreover, these two conditions have an additive role in the progression of carotid atherosclerosis and in blood levels of inflammatory markers for atherosclerosis, such as interleukin-6 and pentraxin-3." (PMID 26697221, 2015). "Moreover, it is associated with increased proinflammatory cytokines (IL-6, TNF-a) that contribute to atherosclerosis and CVD in high-fat composition population." (PMID 26893933, 2015). "In addition to inducing foam cell formation, ox-LDL can activate macrophages to produce proinflammatory cytokines, such as TNF-α, IL-6, and IL-1β, to promote atherosclerosis." (PMID 26045945, 2015). "Additionally, in atherosclerosis, which is an age-associated pro-inflammatory condition, foam macrophages are known to produce higher amounts of TNF-α and IL-6." (PMID 26509710, 2015). "In addition, pro-inflammatory cytokines, including TNF-α and IL-6, which are involved in RA pathogenesis, play a critical role in atherosclerosis in patients with RA." (PMID 25889426, 2015). "In addition, we found that MCP-1, IL-1α and IL-6, which all play an important role in atherosclerosis, were also induced by CC stimulation in primed macrophages." (PMID 24686534, 2014). "Further overproduction of proinflammatory cytokines such as IL-6 or TNF-α could be a marker of chronic inflammation leading to provoked and accelerated atherosclerosis, with a higher risk of CV events and mortality." (PMID 25347067, 2014). "In a large healthy family population study where children were included, IL-6 levels were closely associated with traditional and nontraditional risk factors for atherosclerosis." (PMID 24741576, 2014). "In addition, IL-6, a well-known pro-inflammatory cytokine involved in the pathogenesis of atherosclerosis, was dramatically up-regulated, whereas the serum total cholesterol and IL-6 levels kept stable over the 48-week period in wild type littermates." (PMID 25269085, 2014). "The role of IL-6 and its genetic variants in atherosclerosis is not fully clarified and results of many in vitro, animal model and human studies are controversial." (PMID 25526459, 2014). "There is some evidence that suggests that gp130 cytokine members OSM, and IL-6, may play a role in atherosclerosis." (PMID 24307759, 2013). "IL-6 may inhibit renal mononuclear cell recruitment and the proliferation of mesangial cells, thereby reducing atherosclerosis and improving renal tubular ischemia, reducing proteinuria and improving renal function." (PMID 24137196, 2013). "Among numerous inflammatory markers, C-reactive protein (CRP), predominantly produced by hepatocytes under the stimulation of inflammatory cytokines such as interleukin 6 (IL-6), is one of the most well-validated markers and serves as an independent predictor in various stages of atherosclerosis." (PMID 23950953, 2013). "In addition some studies have analyzed the role of IL-6 in the atherosclerosis process as this marker has a concordance with CRP in the inflammatory response." (PMID 23497664, 2013). "The role of IL-6 in the induction of inflammatory atherosclerosis seems more complex." (PMID 24244577, 2013). "Adipose tissue secretes a number of bioactive molecules, such as resistin, TNF-α, and IL-6 collectively called adipokines, which affect peripheral insulin sensitivity and may be important players in the development of type 2 diabetes and atherosclerosis." (PMID 23484124, 2013). "Studies by others have shown that systemic IL-6 contributes to atherosclerosis development." (PMID 24303000, 2013).
atherosclerosis (continued). "A variety of variables (CRP, complement C3, IL-6 and TNF-α) implicated in the regulation of the inflammatory process and, in turn, in the pathophysiology of arthritides, are relevant in the etiology and the development of atherosclerosis." (PMID 23036698, 2012). "In addition to being involved in the inflammatory process, most cytokines (TNF-α, IL-1, IL-6) play a role in the genesis and in the progression of atherosclerosis." (PMID 23036698, 2012). "In atheromatous plaques and fatty streaks, smooth muscle cells and macrophage foam cells express IL-6, may be an important role for this cytokine in the progression of atherosclerosis." (PMID 21835044, 2011). "One remaining question from our prior studies is why the same cytokines (IL6 or IFN-γ) from another inflammatory cells (e.g. macrophages, T cells, or neutrophils) did not compensate for the loss in mast cells during the pathogenesis of atherosclerosis and AAA." (PMID 21264293, 2011). "TNF-α and IL-6 are critical cytokines that respond to the progression of atherosclerosis." (PMID 21226932, 2011). "Interleukin-8 plays a crucial role in initiating atherosclerosis by recruiting monocytes and macrophages to the vessel wall and has been shown, together with IL-6 and RANTES, to be elevated and to correlate with disease activity in patients with Takayasu's arteritis." (PMID 20842748, 2010). "Although SWCNT exposure was associated with atherosclerosis acceleration, we did not observe significant differences in the plasma levels of IL-6, IL-10, MCP-1, TNF-α, or IFN-γ." (PMID 17431486, 2007). "This may indicate that reduced IL-6 release of LPS-activated T1D monocytes is protective in the development of atherosclerosis." (PMID 16566827, 2006). "Whether other "noxious" pro-atherosclerosis inflammatory factors, such as interleukin-6, play a role in the development of CAD in this cohort remains to be answered." (PMID 17178005, 2006). "The second phase is characterized by advancing atherosclerosis, with greater impact of inflammation as indicated by an elevated level of plasma C-reactive protein, the result of increased production influenced by interleukin-6." (PMID 15574198, 2004). "By targeting IL-6, TCZ not only reduces systemic inflammation but also influences key mediators of cardiovascular risk, such as endothelial dysfunction, monocyte activity, neutrophil extracellular trap (NET) formation (NETosis), and oxidative stress – principal drivers of atherosclerosis and CVD." (PMID 40066438, 2025). "NF-κB also plays a regulatory role in the expression of genes associated with cytokines (e.g., TNF, IL-1, IL-6, IL-8), adhesion molecules (e.g., VCAM-1, ICAM-1, P- and E-selectin) and chemokines (e.g., MCP-1), all of which are implicated in the development of atherosclerosis." (PMID 40076955, 2025). "Similarly, in a rabbit model of atherosclerosis, supplementation with jaboticaba (P. cauliflora) peel decreased plasma levels of IL-1β, IL-6, and soluble intercellular adhesion molecule-1 (sICAM-1) and soluble vascular cell adhesion molecule-1 (sVCAM-1) and reduced atherosclerotic lesions." (PMID 41375968, 2025). "Similarly, colchicine, an anti-inflammatory drug that targets the NLRP3 inflammasome/IL-1β-IL-6 axis, has been effective in reducing cardiac events in patients with atherosclerosis in trials like COLCOT (Colchicine Cardiovascular Outcomes Trial) and LoDoCo2 (Low-Dose Colchicine 2 Trial)." (PMID 40332077, 2025). "Moreover, aberrant signaling via non-mutated JAKs downstream of the IL1B/IL6 signaling axis has been identified as the key driver of vascular disease associated with more frequent drivers of CHIP like mutant TET2 and IL6 blockade allowing mitigation of atherosclerosis." (PMID 40140631, 2025).